MRGPRX2 (MAS related GPR family member X2)
Description:
Mast cell-specific G protein-coupled receptor for basic secretagogues, which regulates mast cell degranulation and itch-related hypersensitivity reactions. A secretagogue is an agent that promotes the secretion of hormones, neurohormones, chemical neurotransmitters or other compounds synthesized and secreted by cells. Basic secretagogues comprise a set of cationic amphiphilic drugs, as well as endo- or exogenous peptides, consisting of a basic head group and a hydrophobic core. Ligand binding causes a conformation change that triggers signaling via guanine nucleotide-binding proteins (G proteins) and modulates the activity of downstream effectors, such as adenylate cyclase. MRGPRX2 is both coupled to G(q) and G(i) G proteins: G(q) coupling activates phospholipase C-beta, releasing diacylglycerol (DAG) and inositol 1,4,5-trisphosphate (IP3) second messengers, while G(i) coupling mediates inhibition of adenylate cyclase activity. Recognizes and binds small molecules containing a cyclized tetrahydroisoquinoline (THIQ), such as non-steroidal neuromuscular blocking drugs (NMBDs), including tubocurarine and atracurium (By similarity). In response to these compounds, mediates pseudo-allergic reactions characterized by histamine release, inflammation and airway contraction (By similarity). Acts as a receptor for substance P, a basic secretagogue neuropeptide released from the terminals of specific sensory nerves, initiating a signaling that mediates neurogenic inflammation and pain. Neurogenic inflammation includes mast cell activation, recruitment of immune cells and release of inflammatory mediators, such as cytokines and chemokines (By similarity). The inflammatory response can then activate or sensitize nociceptors, promoting pain (By similarity). Acts as a receptor for a number of other ligands, including peptides and alkaloids, such as cortistatin-14, proadrenomedullin peptides PAMP-12 and, at lower extent, PAMP-20, antibacterial protein LL-37, PMX-53 peptide, beta-defensins, complanadine A and CXCL17. Also acts as a receptor for opioids, such as (-)- and (+)-morphine, hydrocodone, sinomenine, dextromethorphan, dynorphin A, dynorphin B, and alpha- and beta-neoendorphin, promoting mast cell degranulation.
Synonyms: MRGX2; MGRG3
Tractability: Small molecule: a structure with a bound ligand is known; a high-quality ligand is known; it belongs to a druggable protein family. Antibody: UniProt places it where antibodies can reach, with medium confidence; UniProt predicts a signal peptide or a membrane-spanning region; its Gene Ontology location is reachable by antibodies, with medium confidence. PROTAC: a small molecule that binds it is known.
Target class: Family A G protein-coupled receptor; Membrane receptor
Chemical probes: (R)-ZINC-3573 (high quality)
Safety:
Unwanted effects reported when the protein is acted on. In parentheses: how it was acted on, where the effect was seen, and who reports it.
histamine-like adverse drug reactions (activation; immune; source: Brennan et al. (2024))
Gene: Protein-coding gene on chromosome 11 (19,054,455 to 19,060,717, reverse strand). Ensembl gene ENSG00000183695.
Subcellular location: Cell membrane
Gene Ontology:
Molecular function: C-C chemokine receptor activity; G protein-coupled opioid receptor activity; G protein-coupled receptor activity; mast cell secretagogue receptor activity; neuropeptide binding; protein binding; transmembrane signaling receptor activity
Biological process: adenylate cyclase-inhibiting G protein-coupled receptor signaling pathway; cell migration; chemokine-mediated signaling pathway; mast cell activation; mast cell degranulation; phospholipase C-activating G protein-coupled receptor signaling pathway; positive regulation of cytokinesis; G protein-coupled receptor signaling pathway; positive regulation of chemokine production; positive regulation of cytokine production; positive regulation of neutrophil migration; response to pain; sensory perception of pain; sleep; adenylate cyclase-modulating G protein-coupled receptor signaling pathway; G protein-coupled opioid receptor signaling pathway
Cellular component: plasma membrane; membrane
Genetic constraint (gnomAD): Loss-of-function variants: 0 observed, 0.0869 expected, observed/expected ratio (o/e) 0, 90% interval 0 to 1.89. That is too few expected variants to judge how well the gene tolerates losing a copy. Missense variants: 389 observed, 429.14 expected, observed/expected ratio (o/e) 0.91, 90% interval 0.83 to 0.99. Synonymous variants: 183 observed, 185.8 expected, observed/expected ratio (o/e) 0.98, 90% interval 0.87 to 1.11.
Homologues: Orthologues: chimpanzee MRGPRX2 (96% identical), dog MRGPRX (62% identical), rabbit MGRG2 (56% identical), rat Mrgprx3 (53% identical), mouse Mrgprx2 (53% identical), mouse Mrgpra1 (51% identical), mouse Mrgprb1 (51% identical), mouse Mrgprb2 (51% identical), rat Mrgprb4 (50% identical), rat Mrgprx1 (50% identical), mouse Mrgpra3 (50% identical), mouse Mrgpra9 (50% identical), and 15 more. Paralogues in human: MRGPRX1 (64% identical), MRGPRX3 (62% identical), MRGPRX4 (62% identical), MRGPRD (36% identical), MRGPRF (35% identical), MAS1 (32% identical), MRGPRE (32% identical), MAS1L (31% identical), MRGPRG (28% identical), GPR152 (22% identical).
Diseases named in the same sentence as MRGPRX2 in open-access papers:
MRGPRX2 is named in the same sentence as 61 diseases in open-access papers, as found by Europe PMC text mining. Sharing a sentence is not in itself a finding about the gene and the disease. The quoted sentences say what the papers report.
Allergy (29 papers, 2019 to 2026). An allergy is an immune response or reaction to substances that are usually not harmful. "A recently introduced new classification system of allergic reactions includes tissue-driven allergies (types V and VI) and those induced by direct chemical responses (type VII), with MRGPRX2-associated reactions now reclassified as type VII allergies." (PMID 40254631, 2025). "Additionally, PSB-172656 may be employed as a diagnostic tool for predicting MRGPRX2-mediated drug hypersensitivities, distinguishing them from the typical IgE- and C3a-dependent allergies." (PMID 40254631, 2025). "The mast cell-specific G-protein-coupled receptor (GPCR) MRGPRX2 (Mas-Related G Protein-coupled Receptor X2) has roles in itch and pain, and it mediates clinically relevant allergy-like responses to a diverse assortment of drugs." (PMID 42107641, 2026). "We used an in vitro cultured human mast cell line, Laboratory of Allergic Diseases 2, that constitutively expresses MRGPRX2." (PMID 41886886, 2026). "Receptor dependence of agonist-mediated signal transduction was demonstrated using a CRISPR MRGPRX2 knock down Laboratory of Allergic Diseases 2 cell line and a MRGPRX2 inverse-agonist." (PMID 41886886, 2026). "Until these trials are completed, MRGPRX2 antagonists remain a promising yet experimental option in the field of allergy and immunology." (PMID 40802080, 2025). "MRGPRX2 has emerged as a promising target in the development of new therapies for allergic diseases." (PMID 40918407, 2025). "As a consequence of mediator release upon MRGPRX2-mediated degranulation, symptoms that are very similar to type I allergic reactions can develop and are therefore sometimes called “pseudo-allergic” reactions." (PMID 41516211, 2025). "Surprisingly, and in contrast to the LAD2 (Laboratory of Allergic Diseases 2 mast cell line) MC line, icatibant was at least as potent as SP in eliciting MRGPRX2 internalization and (cross-)desensitization in skin MCs." (PMID 41008531, 2025). "Its effect on MCs was confirmed in cell lines, including rat basophilic leukemia cells (RBL-2H3) recombinantly expressing human MRGPRX2, human Laboratory of Allergic Diseases 2 (LAD2) MCs, and native human skin MCs." (PMID 40254631, 2025). "Temperature monitoring, in vivo hindlimb swelling and exudation test, and in vitro mast cell degranulation test were used to explore the mechanism of MRGPrx2 mediated allergic reaction triggered by M-3." (PMID 39144634, 2024). "Though no news on the development of MRGPRX2-targeting drugs is available to date, the involvement of MRGPRX2 in the IgE-independent mast cell degranulation pathway suggests MRGPRX2 as a potential target for anti-allergy drug development." (PMID 37296626, 2023). "Luteolin can inhibit the FcεRΙ- and MrGPrx2-mediated allergic reaction in vivo and in vitro, and reduce the serum levels of histamine, TNF-α, MCP-1, IL-8 and IL-13 in mice." (PMID 36611103, 2023). "In the present review, we have comprehensively searched all of the relevant databases (PubMed, Science Direct, and Google Scholar) for the terms MRGPRX2, MRGPRX2 and allergy, pseudo-allergic reactions, and mast cell GPCR from 2006 to March 2021." (PMID 33925682, 2021). "Several GPCRs such as C5AR1, C3AR1, and recently identified MRGPRX2 can induce exocytosis, allergies, and anaphylactic responses." (PMID 33925682, 2021). "The MRGPRB2 knockout model has provided direct evidence of the involvement of MRGPRB2/MRGPRX2 in pseudo allergies, itch, and rosacea." (PMID 33925682, 2021). "Recently, several findings have demonstrated the mechanism and role of MRGPRX2 in NMBAs-induced preoperative pseudo-allergic reactions." (PMID 33925682, 2021). "While IgE-FcεRI-mediated MC activation is an eminent and more studied mechanism in allergic diseases, recent studies demonstrated the crucial role of MRGPRX2 in the IgE-independent MC activation mechanism and allergic diseases." (PMID 33925682, 2021).
Allergy (continued). "Osthole also inhibits MrgprB2- (mouse ortholog of human MRGPRX2) dependent inflammation in in vivo mouse models of pseudo-allergy." (PMID 32391014, 2020). "Recently some natural compounds such as quercetin, saikosaponin A, and shikonin have been reported to inhibit mast cell degranulation and inhibit MRGPRX2-induced pseudo allergic reactions." (PMID 32106575, 2020). "This is highly significant in situations where individuals experience both IgE-dependent and IgE-independent allergic reactions because osthole treatment will result in attenuation of mast cell activation via both MRGPRX2 and IgE receptors." (PMID 32391014, 2020). "Thus, the worsening cycle (MRGPRX2 → CTMC degranulation → chymase → DRG activation → SP → MRGPRX2) contributes to vascular hyperpermeability in MRGPRX2-KI mice in pseudo-allergy models, which is a novel point." (PMID 39640264, 2024). "Furthermore, this study showed that osthole affects both the surface and intracellular expression levels of MRGPRX2, providing another possible way to regulate the MRGPRX2 response in allergic reactions and rosacea." (PMID 38535499, 2024). "MRGPRX2 is a protein predominantly found on skin mast cells, sensory neurons, and keratinocytes, and its activation on mast cells leads to IgE-independent manifestations resembling type 1 hypersensitivity (pseudo-allergic reactions)." (PMID 39768474, 2024). "In addition, skin MCs are major effector cells in anaphylaxis, the most severe clinical presentation of an acute allergic reaction, of which IgE-dependent and IgE-independent forms exist, the latter encompassing MRGPRX2 activation by a broad spectrum of drugs." (PMID 39451199, 2024). "MRGPRX2 is expressed predominantly in mast cells and activated by a broad range of cationic ligands, including substance P and hemokinin-1, which is subsequently involved in the development of allergic diseases." (PMID 35733520, 2022). "In summary, we demonstrated that paroxetine and a related GRK2 inhibitor not only have an attractive clinical prospect in targeting allergic reactions, but also may serve to enhance host defense via MRGPRX2/MRGPRB2 activation." (PMID 36275707, 2022). "Additionally, accumulating evidence suggests the crucial role of MRGPRX2 in the neuroimmune interaction and the pathophysiology of allergic diseases such as chronic urticaria, allergic rhinitis, asthma, and food allergy." (PMID 33925682, 2021). "However, the crucial pathophysiological roles of MRGPRX2 in allergic and non-allergic diseases remain poorly understood." (PMID 33925682, 2021). "A natural plant compound such as osthole that targets MRGPRX2, may thus provide a safer alternative to treat pseudo-allergic conditions over the current allergy therapies available." (PMID 32391014, 2020). "Importantly, SOCE also critically modulates MrgprB2 (mouse ortholog of human MRGPRX2) dependent inflammation in in vivo mouse models of pseudo-allergy." (PMID 32038646, 2019). "In addition, the pathology of several allergic diseases such as asthma and urticaria correlate with mast cell-specific expression of MRGPRX2." (PMID 32038646, 2019). "Since its identification as a receptor that mediates IgE-independent activation of MCs, interest in MRGPRX2 and its signaling pathways has been growing, which has contributed greatly to a better understanding of the previously unresolved issue of hypersensitivity and pseudo-allergic reactions." (PMID 41516211, 2025). "This suggests that MRGPRX2 inhibitors may become a therapeutic strategy in allergic diseases." (PMID 39104520, 2024). "Given that SOCE via STIM1 promotes responses of FcεRI and MRGPRX2, two important mast cells receptors that mediate allergy in humans; future studies designed to characterize this mechanism further may lead to the development of novel therapeutic approaches for the treatment of allergic diseases." (PMID 32038646, 2019).
Allergy (continued). "Its classification as biased is based on studies in cell lines such as the HEK293-derived TANGO Luciferase Assay cell line (HTLA) and the Laboratory of Allergic Diseases 2 mast cell line (LAD2), naturally expressing MRGPRX2, or MRGPRX2 transfectants." (PMID 41008531, 2025). "To assess the activation of human MRGPRX2 by PACAP1-38, we used Laboratory of Allergic Diseases 2 (LAD2) cells, an immortalized human mast cell line that expresses MRGPRX2." (PMID 37516794, 2023). "In the present article, we reviewed the emerging role of MRGPRX2 as a non-IgE-mediated mechanism of mast cell activation in pseudo-allergic reactions." (PMID 33925682, 2021). "The puzzle of non-IgE-mediated pseudo-allergic reaction is unlocked by MRGPRX2, evidenced by a plethora of reported endogenous and exogenous MRGPRX2 agonists." (PMID 33925682, 2021). "These non-canonical characteristics render MRGPRX2 an intriguing player in allergic diseases." (PMID 33925682, 2021). "Interestingly, the MC stabilizing H1 antihistamine ketotifen was shown to directly inhibit both IgE- and MRGPRX2-dependent activation, expanding upon previous research and supporting its use in both IgE-dependent allergy as well as non-IgE-dependent disorders such as clonal MC disorders." (PMID 39737168, 2024). "Molecular docking analyses suggested that osthole could not compete with MRGPRX2 agonists, but rather regulated MRGPRX2 activation through allosteric modification, mainly by attenuating Ca2+ mobilization in vitro and inhibiting inflammation in mouse models of pseudo-allergy." (PMID 40098666, 2025).
anaphylaxis (25 papers, 2020 to 2025). An acute hypersensitivity reaction that occurs from exposure to an allergen. "The current study explores the mechanistic prerequisites underlying MRGPRX2-elicited degranulation in dermal MCs, i.e., the acute process behind hypersensitivity, urticaria and anaphylaxis." (PMID 35326404, 2022). "Perhaps the most straightforward explanation behind the rare, proposed heightened sensitivity of some individuals to MRGPRX2-dependent anaphylaxis is receptor polymorphism." (PMID 34867939, 2021). "Tandem testing of MRGPRX2 allele expression, drug concentrations, and IgE titers in patients with anaphylaxis would be extremely informative; unfortunately, these tests are rarely conducted and most MRGPRX2 alleles remain uncharacterized." (PMID 34421893, 2021). "In the case of small-molecule drugs, MC degranulation occurs under in vitro experimental conditions, which may cause MRGPRX2-related systemic pseudo-allergic reactions, particularly acute urticaria and anaphylaxis." (PMID 36341461, 2022). "Whether anaphylaxis in ISM patients is linked to IgE-dependent or MRGPRX2-dependent MC activation or both mechanisms needs to be investigated in further studies." (PMID 35958589, 2022). "Additionally, it was recently proposed that Hymenoptera venom and medications such as quinolone antibiotics can cause non–IgE-mediated anaphylaxis through the activation of Mas-related G protein-coupled receptor X2 (MRGPRX2) on mast cells." (PMID 36569939, 2022). "It is possible that an elevated or more diverse tissue expression of MRGPRX2, perhaps associated with disease, may enhance an individual’s susceptibility to drug-induced anaphylaxis." (PMID 34867939, 2021). "Assuming an appropriate evidence-base, and predictive test, such compounds could in theory also serve as prophylactic agents to minimize MRGPRX2-dependent anaphylaxis risk, particularly in the perioperative setting." (PMID 34867939, 2021). "Although these findings highlight the role of the mast cell-MRGPRX2 axis in causing anaphylaxis and inflammation associated with urticaria, asthma and rosacea, there is limited information available on how MRGPRX2 can be targeted to prevent these adverse reactions/diseases in humans." (PMID 32391014, 2020). "Skin MCs express MRGPRX2 at highest level across the body and are of pathophysiological significance in skin diseases and systemic reactions like anaphylaxis, in which skin symptoms are dominant." (PMID 41008531, 2025). "The efficacy and safety of MRGPRX2 antagonism in human is still unproven, and more extensive clinical trials are required to evaluate their potential as therapeutic agents in human anaphylaxis management." (PMID 40802080, 2025). "The results indicate that the M-3 metabolite can activate mast cells synergistically with its prototype SH via MRGPRX2 and aggravate anaphylaxis." (PMID 39144634, 2024). "The description of patients presenting anaphylaxis when exposed to one or multiple MRGPRX2 agonists such as general anesthetics, antibiotics, opiods and other agents has provided evidence of potential heterogeneity in humans." (PMID 39585499, 2024). "The aim of this study was to clarify the mechanism by which metabolites and prototype drugs trigger anaphylaxis through the activation of mast cells by MRGPRX2." (PMID 39144634, 2024). "On the other hand, some TCM compounds were reported to indicate protective effects against MRGPRX2-dependent anaphylaxis and chronic skin disorders." (PMID 38535499, 2024). "On the other hand, despite relatively recent discovery, evidence has accumulated to suggest important contributions of MRGPRX2 to skin diseases like AD, psoriasis, and anaphylaxis, the latter especially when induced by drugs." (PMID 38067128, 2023). "The role and relevance of MRGPRX2 and its agonists for the elicitation of anaphylaxis and intolerance reactions to different triggers, e.g., drugs, in ISM should be addressed in future studies." (PMID 35958589, 2022).